PDIA5 (protein disulfide isomerase family A member 5)
Synonyms: PDIR; FLJ30401
Tractability: Antibody: UniProt predicts a signal peptide or a membrane-spanning region. PROTAC: ubiquitination databases record sites on it; its protein half-life has been measured.
Target class: Isomerase; Enzyme
Gene: Protein-coding gene on chromosome 3 (123,067,025 to 123,225,227, forward strand). Ensembl gene ENSG00000065485.
Subcellular location: Endoplasmic reticulum lumen
Subcellular location (Human Protein Atlas): Endoplasmic reticulum
Pathways (Reactome):
Cellular responses to stimuli: XBP1(S) activates chaperone genes
Gene Ontology:
Molecular function: protein binding; protein disulfide isomerase activity; protein-disulfide reductase activity; oxidoreductase activity
Biological process: protein folding; electron transport chain
Cellular component: endoplasmic reticulum lumen; endoplasmic reticulum membrane
Genetic constraint (gnomAD): Loss-of-function variants: 38 observed, 55.45 expected, observed/expected ratio (o/e) 0.69, 90% interval 0.53 to 0.9. The upper end of that interval is the gene's LOEUF score, 0.9, which puts it in group 3 of 6, group 1 being the genes least tolerant of losing a copy. Missense variants: 476 observed, 518.22 expected, observed/expected ratio (o/e) 0.92, 90% interval 0.85 to 0.99. Synonymous variants: 201 observed, 205.28 expected, observed/expected ratio (o/e) 0.98, 90% interval 0.87 to 1.1.
Homologues: Orthologues: chimpanzee PDIA5 (99% identical), macaque PDIA5 (99% identical), dog PDIA5 (94% identical), pig PDIA5 (93% identical), rabbit PDIA5 (92% identical), rat Pdia5 (90% identical), mouse Pdia5 (90% identical), guinea pig PDIA5 (89% identical), tropical clawed frog pdia5 (65% identical), zebrafish pdia5 (64% identical), Drosophila melanogaster CG9302 (42% identical), Caenorhabditis elegans pdi-1 (18% identical), and 1 more. Paralogues in human: P4HB (21% identical), PDIA4 (21% identical), PDIA2 (20% identical), PDIA3 (20% identical), TXNDC5 (18% identical), PDILT (16% identical), PDIA6 (14% identical), TXNDC11 (13% identical), TMX3 (13% identical), ERP44 (12% identical), TMX1 (8% identical), TMX4 (7% identical), and 1 more.
Diseases named in the same sentence as PDIA5 in open-access papers:
PDIA5 is named in the same sentence as 46 diseases in open-access papers, as found by Europe PMC text mining. Sharing a sentence is not in itself a finding about the gene and the disease. The quoted sentences say what the papers report.
glioma (10 papers, 2012 to 2024). A benign or malignant brain and spinal cord tumor that arises from glial cells (astrocytes, oligodendrocytes, ependymal cells). "For example, based on scRNA-seq analysis, PDIA5 (Protein Disulfide Isomerase Family A Member 5) has been identified as associated with worse glioma outcomes and induction of macrophage infiltration." (PMID 36119086, 2022). "It is particularly noteworthy that PDIA5 overexpression correlates with immune infiltration and is associated with poor prognosis in glioma patients." (PMID 33664747, 2021). "Altogether, our findings indicate that PDIA5 overexpression is associated with immune infiltration in gliomas, and may be a promising therapeutic target for glioma immunotherapy." (PMID 33664747, 2021). "Therefore, we deduced that high expression of PDIA5 may induce macrophage associated immunity, and contribute to M2 polarization of macrophage in gliomas." (PMID 33664747, 2021). "Although the correlations between PDIA5 overexpression and immune infiltration in gliomas have been revealed, the impact of PDIA5 on the tumor immunity of human cancers have seldomly been explored systematically." (PMID 36003400, 2022). "Based on large-scale bioinformatic analysis, we are the first to comprehensively analyze PDIA5 expression profiles in gliomas according to the WHO grading system, histopathology, molecular biomarkers, and molecular subclasses." (PMID 33664747, 2021). "Analysis of the prognostic significance of PDIA5 in different types of gliomas under the 2016 WHO classification of CNS tumors demonstrated that patients with low PDIA5 expression experienced longer OS regardless of the subtypes." (PMID 33664747, 2021). "In TCGA datasets, there was positive correlation between PDIA5 and CD276 or PDCD1LG2 in pan-glioma patients, and PDIA5 expression was positively associated with CD276, PDCD1LG2 and HAVCR2 in LGG patients." (PMID 33664747, 2021). "Based on large-scale bioinformatics analysis, we discovered that PDIA5 expression level is upregulated in aggressive gliomas, with high PDIA5 expression predicting poor clinical outcomes." (PMID 33664747, 2021). "Accordingly, these results demonstrated that PDIA5 high glioma cells functionally promoted tumor cell proliferation and exhausted immune cells (HMC3)." (PMID 33664747, 2021). "Accumulating evidence of the correlation between PDIA5 and macrophages in glioma microenvironment drove us to investigate the in-depth mechanisms involved in the interconnection among PDIA5, glioma cells, and macrophages." (PMID 33664747, 2021). "Further analysis attested the positive correlation between PDIA5 and macrophage, especially M2, infiltration in gliomas." (PMID 33664747, 2021). "Then we continued to conduct correlation analysis between PDIA5 and immunity pathways in gliomas using GO." (PMID 33664747, 2021). "Protein levels of PDIA5 were examined via IHC staining in the gliomas and normal brain tissue samples from Xiangya Hospital (n=34)." (PMID 33664747, 2021). "We found tight correlations between PDIA5 and B7-H3, PD-L2, and TIM-3, suggesting that PDIA5 probably plays a synergistic role with those immune checkpoints in the progression of glioma." (PMID 33664747, 2021). "Taken together, these results suggest that high PDIA5 expression level was relevant to stromal and immune cell infiltration in the tumor microenvironment of gliomas." (PMID 33664747, 2021). "Amplification of chr7 and deletion of chr10 consistently appeared in gliomas with high PDIA5 expression." (PMID 33664747, 2021). "To further elucidate the immune infiltrating role of PDIA5, we also analyzed the expression of PDIA5 in gliomas using scRNA-seq." (PMID 33664747, 2021). "In CGGA dataset, PDIA5 expression was positively associated with CD276, CD274, PDCD1LG2, and HAVCR2 in pan-glioma and LGG patients, and positively correlated with CD276, PDCD1, CD274, PDCD1LG2, and HAVCR2 in GBM patients." (PMID 33664747, 2021).
glioma (continued). "In our research, we found these three ESTIMATE algorithm scores were increased along with PDIA5, indicating that high expression level of PDIA5 is positively correlated with immune infiltration in gliomas." (PMID 33664747, 2021). "Cell transfection and co-culture of glioma cells and macrophages revealed that PDIA5 in tumor cells mediated macrophages exhausting." (PMID 33664747, 2021). "Altogether, our results imply that PDIA5 has positive correlation with clinically relevant immune checkpoint molecules in gliomas." (PMID 33664747, 2021). "This phenomenon can be attributed to the fact that the glioma cells with high expression of PDIA5 secrete certain cytokines to recruit M2 macrophages, which interact with glioma cells and potentially ended with apoptosis and degradation." (PMID 33664747, 2021). "And the correlation between PDIA5 and T cells as well as macrophages in gliomas was presented in the subsequent specific analysis." (PMID 33664747, 2021). "Subsequently, we analyzed the effect of PDIA5 on the prognosis of gliomas in the context of different molecular biomarkers and treatments." (PMID 33664747, 2021). "In gliomas, PDIA5 had significantly increased expression in gliomas compared with normal brain tissues." (PMID 33664747, 2021). "The qRT-PCR and immunohistochemistry confirmed that P4HB, PDIA4 and PDIA5 were overexpressed in gliomas." (PMID 32023222, 2020). "Among the 33 cancers, the top three cancers with the most remarkable correlation between PDIA5 expression and stromal score were lower-grade glioma (LGG), BLCA, and thymoma (THYM), the top three tumors whose PDIA5 expression was most notably associated with immune score were LGG, PRAD and BLCA." (PMID 36003400, 2022). "However, basic research is needed to further investigate the specific interactions between PDIA5 and the immune system in gliomas." (PMID 33664747, 2021). "Additionally, 1p/19q codeletion more frequently occurred in gliomas with low PDIA5 expression, and 63 and 30 significant genomic events were discovered in the high and low PDIA5 groups respectively." (PMID 33664747, 2021). "In summary, our results revealed that PDIA5 expression is upregulated in aggressive gliomas." (PMID 33664747, 2021). "Investigating the detailed mechanism of PDIA5 promotion of glioma development may help to develop new therapeutic strategies." (PMID 33664747, 2021). "Additionally, in pan-glioma patients, there was a positive correlation between PDIA5 expression and six metagenes other than IgG." (PMID 33664747, 2021). "In the present study, we comprehensively analyzed the PDIA5 expression pattern in gliomas." (PMID 33664747, 2021). "We subsequently analyzed the expression level of PDIA5 in the 8 glioma samples." (PMID 33664747, 2021). "Furthermore, knock-down PDIA5 presented the malignant behavior decreasing of glioma cells in immune cells exhausting." (PMID 33664747, 2021). "Therefore, the high level of PDIA5 expression in gliomas indeed contribute to recruiting macrophages and probably mediating the polarization of macrophages to M2." (PMID 33664747, 2021). "Notably, glioma patients with low PDIA5 level experienced favorable outcomes among the glioma patients." (PMID 33664747, 2021). "We further assessed the prognostic value of PDIA5 in glioma patients from TCGA and CGGA." (PMID 33664747, 2021). "Taken together, our findings demonstrate that PDIA5 overexpression correlates with immune infiltration and inflammation in gliomas, which may lead to poor prognosis in glioma patients." (PMID 33664747, 2021). "Subsequently, we investigated whether PDIA5 could predict glioma patients’ responses to checkpoint inhibitor immunotherapy in anti-CTLA-4 and anti-PD-1 based on CGGA and TCGA datasets, and found that compared with low PDIA5 group, high PDIA5 group was expected to respond better to immunotherapies." (PMID 33664747, 2021). "Overall, these findings indicate that PDIA5 could be a promising target for glioma immunotherapy." (PMID 33664747, 2021).
glioma (continued). "PDIA5 was found to be upregulated in gliomas and related to the suppressive tumor microenvironment by recruiting M2 macrophages, indicating that PDIA5 might be a potential prognostic biomarker or therapy target in the clinical treatment of gliomas." (PMID 33664747, 2021). "Specifically, previous studies described the ability of several molecular markers involved for predicting the prognosis of glioma and these molecular markers include MEOX2, PDIA5, and DDX3X." (PMID 39012280, 2024). "We also performed PDIA5 over-expression and siRNA on U251 then co-culturing with HMC3 in vitro to mimic the infiltration of residential immune cells in glioma microenvironment." (PMID 33664747, 2021). "We detected PDIA5 expression in GBM and pan-gliomas samples from the TCGA dataset and found that increased PDIA5 expression was associated with the CL and ME molecular subtypes." (PMID 33664747, 2021). "Among pan-glioma, LGG, and GBM in the TCGA dataset, patients with higher PDIA5 levels presented shorter OS, DSS, and PFI compared to patients expressing low levels of PDIA5, with the exception of GBM which was not statistically significant for OS." (PMID 33664747, 2021). "PDIA5 protein is the member of PDI family, which is highly expressed in glioma and participates in glioma progression." (PMID 33664747, 2021). "In this study, we have shown that the expression of PDIA5 and TXNDC12 was positively correlated with high‐grade gliomas, as well as with wild‐type IDH status and 1p/19q non‐codeletion." (PMID 32301283, 2020). "All four genes, P4HB, PDIA4, PDIA5, and TXNDC12, were expressed in glioma cell lines, and these genes were differentially expressed in different cell lines (U251, T98G, A172, U343)." (PMID 32023222, 2020). "We explore the differences in PDIA5 expression between various types of types of GBM tissue cells by conducting single-cell sequencing data analysis, which included sequencing data from 13 patients with GBM and 18 patients with lower-grade glioma (LGG)." (PMID 39247813, 2024). "PDIA5 expression level was higher in GBM (WHO grade IV) compared to LGG (WHO grade II and grade III), and it was elevated in malignant histopathologic gliomas." (PMID 33664747, 2021). "Moreover, a positive relationship was observed in correlation analysis between PDIA5 and CD68 in gliomas patients from TCGA dataset." (PMID 33664747, 2021). "Generally, existing data regarding the action mechanism of PDIA5 to interfere with the immune system is relatively lacking, and more wet experiments are needed to further interpret the role of PDIA5 in gliomas immunology." (PMID 33664747, 2021). "Therefore, we analyzed the correlation between PDIA5 expression and immune infiltration using ESTIMATE, and discovered positive correlation between PDIA5 expression and stromal score, immune score, and ESTIMATE score in pan-glioma and GBM patients." (PMID 33664747, 2021). "Despite the negative association between PDIA5 and IgG indicate PDIA5 inhibition of IgG activity, which might only represent part of the B cells, PDIA5 promotion of malignancy attract more immune cells including B cells in the tumor microenvironment of gliomas." (PMID 33664747, 2021). "Additionally, immunohistochemistry revealed that PDIA5 and macrophage biomarker CD68 were upregulated in high-grade gliomas, and patients with low PDIA5 level experienced favorable outcomes among 33 glioma patients." (PMID 33664747, 2021). "Furthermore, PDIA5 can promote ATF6 disulfide bond rearrangement of ATF6α under ER stress, maintaining its active conformation, and conferring chemotherapy resistance to cancer cells, thus affecting the progression of patients with glioma 19,20." (PMID 39247813, 2024). "Moreover, PDIA5 expression was upregulated in the MGMT promoter non-methylated samples of pan-glioma patients." (PMID 33664747, 2021).
glioblastoma (3 papers, 2020 to 2024). The most malignant astrocytic tumor (WHO grade IV). "To further validate whether PDIA5 influences glioblastoma malignancy through CCAR1 in vivo, we injected stable transfected U87 cell lines (shCtrl, shPDIA5-1, shPDIA5-2, shPDIA5-1+LV-CCAR1 and shPDIA5-2+LV-CCAR1) into the brain of nude mice using a stereotaxic instrument to form intracranial GBMs." (PMID 39247813, 2024). "We also demonstrated the interaction between PDIA5 and immune cells in glioblastoma multiforme (GBM)." (PMID 36003400, 2022).
leukemia (3 papers, 2018 to 2022). A malignant (clonal) hematologic disorder, involving hematopoietic stem cells and characterized by the presence of primitive or atypical myeloid or lymphoid cells in the bone marrow and the blood. "And the PDIA5/ATF6 signaling is correlated with the resistance to chemotherapy in leukemia cells, suggesting the pro-survival effect of PDIA5 in cancers." (PMID 36003400, 2022). "For example, as one of the three major effectors of UPR, ATF6α activation plays a vital role in conferring imatinib resistance on leukemia cells, which is regulated by protein disulfide isomerase A5 (PDIA5)." (PMID 30413206, 2018). "For example, PDIA5 modulated resistance of leukemia cells to imatinib treatment." (PMID 34781823, 2021).
mesothelioma (2 papers, 2021 to 2022). A usually malignant and aggressive neoplasm of the mesothelium which is often associated with exposure to asbestos. "There were positive correlations between the expression level of PDIA5 and MMR genes in most cancers except DLBC, GBM, acute myeloid leukemia (LAML), mesothelioma (MESO), sarcoma (SARC), and uterine carcinosarcoma (UCS)." (PMID 36003400, 2022).
Barrett esophagus (1 paper, 2012). Esophageal lesion lined with columnar metaplastic epithelium which is flat or villiform. "Interestingly, PDIA5 is also up-regulated in Barrett’s esophagus, a disorder in which mucus-producing cells are a basic pathologic change." (PMID 22676183, 2012).
cervical squamous cell carcinoma (1 paper, 2022). A squamous cell carcinoma arising from the cervical epithelium. "More specifically, PDIA5 showed homozygous amplification in cervical squamous cell carcinoma and endocervical adenocarcinoma (CESC), LUSC, and OV." (PMID 36003400, 2022).
colon cancer (1 paper, 2022). "Consistent with previous reports, PDIA1 and PDIA3 were overexpressed in colon cancer tissues in comparison with that in their adjacent tissues, in addition to the overexpressed PDIA2; however, no statistic changes were detected for PDIA4, PDIA5, and PDIA6 expression." (PMID 35860571, 2022).
diffuse large B-cell lymphoma (1 paper, 2022). "Significantly, we observed positive correlations between PDIA5 and TMB in BLCA, COAD, HNSC, LUSC, and TGCT, and negative correlation in diffuse large B-cell lymphoma (DLBC), LIHC, and PRAD." (PMID 36003400, 2022).
glaucoma (1 paper, 2014). Increased pressure in the eyeball due to obstruction of the outflow of aqueous humor. "The goal of the current study is to investigate the role of these two genes, protein disulphide isomerase A member 5 (PDIA5) and baculoviral IAP repeat containing 6 (BIRC6), in different forms of glaucoma." (PMID 25118708, 2014).
laryngeal squamous cell carcinoma (1 paper, 2022). A squamous cell carcinoma that arises from the larynx. "Using pan-cancer samples, we detected the PDIA5 expression in laryngeal squamous cell carcinoma (LSCC), THCA, BLCA, urinary tract urothelial carcinoma (UTUC), LGG, GBM, UCEC, CESC, ovarian serous papillary cystadenocarcinoma (OPV), OV, penis squamous cell carcinoma (PSCC), TGCT, and PRAD." (PMID 36003400, 2022).
leishmaniasis (1 paper, 2021). Infectious disease that is transmitted through the bite of hematophagous female phlebotomine sand flies. "So far, no previous studies have focused on the interaction between PDIA5 and tumor immunity, but a few studies on PDI and immune cells have demonstrated that PDI can elicit CD8+ T-cells in leishmaniasis." (PMID 33664747, 2021).
malignant glioma (1 paper, 2021). A grade III or grade IV glioma arising from the central nervous system. "In summary, our findings demonstrate that PDIA5 is upregulated in multiple types of malignant gliomas, and has multifaceted prognostic value in cancers." (PMID 33664747, 2021).
melanoma (1 paper, 2022). A malignant, usually aggressive tumor composed of atypical, neoplastic melanocytes. "The most significant differences in melanoma are NOMO1, PIGT, VKORC1, PDIA5 and DDX11, and the most significant differences in uterine cancer are CTU2, EMC8, TUBG1, CLPP and LONP1." (PMID 34951103, 2022).
metastatic melanoma (1 paper, 2021). A melanoma that has spread from its primary site to another anatomic site. "Then we continued to analyze the predictive value of PDIA5 regarding the response of anti-PD-L1 (IMvigor210) and anti-PD-1 (GSE78220) therapy for urothelial cancer and metastatic melanoma cohorts, respectively." (PMID 33664747, 2021).
pancreatic cancer (1 paper, 2024). "In the course of cancer therapy, PDIA5 can interact with RNASET2 to resist the killing ability of drugs on pancreatic cancer cells." (PMID 39247813, 2024).
paraganglioma (1 paper, 2022). A benign or malignant neoplasm arising from paraganglia located along the sympathetic or parasympathetic nerves. "PDIA5 was notably related to immune checkpoint genes in multiple cancer types, such as GBM, kidney chromophobe (KICH), KIRP, LGG, pheochromocytoma, paraganglioma (PCPG), PRAD, and THYM, indicating the potentiality of PDIA5 to regulate tumor immunity in these cancers." (PMID 36003400, 2022).